INS (insulin)
Diseases named in the same sentence as INS in open-access papers (continued):
Sharing a sentence is not in itself a finding about the gene and the disease.
diabetes (continued). "Diabetes is a crucial public health issue that is demarcated with insufficient carbohydrate metabolism, protein, and fat due to erratic insulin secretion, insulin resistance secretion, autoimmune response, and pregnancy." (PMID 36268322, 2022). "In our previous investigation, we found that AhR regulated the energy balance, insulin sensitivity, and glucose metabolism in the diabetes condition involved in the regulation of the VEGFβ- and TGFα pathway." (PMID 36232555, 2022). "Diabetes is a metabolic disease characterized by hyperglycemia due to insulin secretion defects and/or insulin dysfunction." (PMID 36120375, 2022). "Diabetes is a metabolic disease characterized by in mpaired ability to produce or respond to insulin that results in hyperglycemia, which can become severe and lead to numerous serious health complications." (PMID 36432144, 2022). "Fewer patients with diabetes in Asia were treated with insulin and/or biguanides, and roughly twice as many patients in Asia were treated with dipeptidyl peptidase-4 inhibitors compared with patients in Europe or Latin America." (PMID 35497805, 2022). "The main cause of type 2 diabetes mellitus (T2DM) is dysfunction of insulin secretion in pancreatic β-cells and insulin resistance in skeletal muscle, liver and fatty tissue." (PMID 36129576, 2022). "Glomerular hyperfiltration observed in early diabetes and metabolic effects of high insulin levels have been proposed as mechanisms for low Hcy." (PMID 34601603, 2022). "In the United States, rising list prices on rapid-acting insulin analogs such as Humalog and NovoLog insulin have resulted in a substantial cost burden for patients with diabetes." (PMID 35156937, 2022). "IR is a condition in which a particular concentration of insulin produces a less-than-expected biological effect; that makes up a broad clinical spectrum including diabetes, obesity, and metabolic syndrome, which will affect the patient's quality of life." (PMID 36002887, 2022). "Regarding diabetes treatments, subjects in the HG received a lower total dose of daily insulin and prandial insulin than subjects in the NHG." (PMID 36191264, 2022). "This study assessed the effects of adjuvant diabetes medications on glycated hemoglobin (A1C), body mass index (BMI), or total daily insulin (TDI) among patients with T1D in a real-world setting." (PMID 36005937, 2022). "Diabetes mellitus is a metabolic disease characterized by chronic hyperglycemia that arises from the impaired secretion and/or action of insulin in its target tissues." (PMID 36499613, 2022). "Depression in patients with arthritis is related to treatment other than medication, and depression in patients with diabetes is related to insulin injections." (PMID 35538471, 2022). "Drosophila insulin signaling, despite having eight insulin-like peptides with partially redundant functions, is very similar to the human insulin pathway and has served as a model to study many different aspects of diabetes and the diabetic state." (PMID 35782067, 2022). "Cumulative incidence over 36 months from the time of progression of diabetes varied by definition of progression and by sex, with insulin-initiating males showing the highest incidence of PDAC diagnosis (0.37%)." (PMID 34728468, 2022). "In the two diabetes model mice, Gys1 in the muscle of the mice in the combination group was significantly enhanced, indicating that the combination of 2-O-M and insulin can significantly enhance the glycogen synthesis of the muscle in both models." (PMID 35502441, 2022). "A total of 986 drugs were prescribed for diabetes including insulin with a mean of 2.8 ± 1.14 antidiabetic drugs prescribed per prescription (n = 351)." (PMID 35308676, 2022). "The duration of diabetes (p < .0001) and the total daily dose of insulin (p = .012) were significantly higher in patients with LT T1D compared to NC‐T1D individuals." (PMID 36169248, 2022).
diabetes (continued). "Recently, it has been demonstrated that activity of the polyamines-hypusine circuit in insulin-producing islet β cells contributes to diabetes pathogenesis under conditions of inflammation." (PMID 35448531, 2022). "We evaluated the sex-specific association between low muscle mass and glucose fluctuations in hospitalized patients with type 2 diabetes mellitus (T2DM) receiving continuous subcutaneous insulin infusion (CSII) therapy." (PMID 35909561, 2022). "Sex hormones play a role, at least in part, in these sex differences by regulating glucose homeostasis, insulin secretion, and action as well as influencing the progression of diabetes and various complications." (PMID 36012115, 2022). "Data collected from the SWEET registry, including 16,570 youth with type 1 diabetes mellitus, reported that the participants who used insulin pumps achieved better glycemic control with lower insulin doses than those using multiple daily injections." (PMID 36422210, 2022). "The beneficial effects of ASA have been reported to be multifactorial and mediated by interfering with inflammation, oxidative stress, mitochondrial dysfunction, insulin secretion, insulin sensitivity and signaling and regulating energy metabolism in diabetes." (PMID 35054496, 2022). "Sulfonylureas are a class of oral anti-diabetes agents that stimulate the release of insulin from pancreatic β cells." (PMID 35204778, 2022). "The greatest interest of researchers is the study of insulin disorders and the development of various forms of diabetes." (PMID 36313742, 2022). "Endocrinologists/diabetes physicians are usually the initiator of insulin treatment when indicated for women with GDM in New Zealand." (PMID 35960738, 2022). "For some people with intellectual disabilities, physical disability made diabetes management with insulin more challenging according to three papers." (PMID 35983585, 2022). "It attenuates glucose tolerance, increases serum insulin levels, and increases blood glucose levels in a mouse model of diabetes." (PMID 36144741, 2022). "Patients expressing these mutations oftentimes have transient neonatal hyperinsulinemia hypoglycemia, progressive hypoglycemia throughout childhood, gradual decrease in insulin secretion, and diagnosis with diabetes mellitus before the age of 25." (PMID 36573710, 2022). "We report a case of a 62-year-old woman with pre-existing type 2 diabetes mellitus of 10 years duration who developed type 3 hypersensitivity reaction to insulin analogue detemir, and subsequently, severe diabetic ketoacidosis (DKA)." (PMID 35350098, 2022). "Chronic disruption of insulin-glucose homeostasis results in hyperglycemia, hyperinsulinemia, and insulin resistance; these pathophysiologic abnormalities precede the onset of diabetes." (PMID 36490255, 2022). "For example, people who inject themselves with medication, such as people with diabetes who require insulin, are affected by trypanophobia (needle phobia)." (PMID 35078432, 2022). "As a consequence, there is a curtailment in bone mass in individuals with diabetes due to a defect in insulin production/resistance." (PMID 36362238, 2022). "The patient population was complex, with 50.8% (n=128) carrying a diagnosis of hypertension requiring medication and 20.2% (n=51) with diabetes (both insulin- and non-insulin-dependent)." (PMID 36494765, 2022). "This is one of the first nationally representative studies to characterize glycemic control and severe hyperglycemia among US adults with diabetes using insulin." (PMID 36538330, 2022). "Although insulin requires frequent monitoring to maintain proper glucose levels, it remains to be the drug of choice in patients with diabetes and COVID-19." (PMID 36051728, 2022). "In patients with T2DM, decreased muscle mass leads to deteriorated insulin sensitivity, aggravated diabetes, increased somatostatin secretion, abnormal bone metabolism, and reduced bone mass, and is associated with osteoporosis." (PMID 36337638, 2022).
diabetes (continued). "In one case, a person with diabetes described having an “insulin dealer” who provided insulin at a cheaper cost than when using insurance." (PMID 35436214, 2022). "Many studies reviewed in this paper suggest that myokine-induced AMPK signalling increases insulin sensitivity and glucose uptake to reduce hyperglycemia and counteract the effects of obesity and diabetes." (PMID 36479347, 2022). "Despite the advancements in oral drug therapy for the management of diabetes mellitus, the mainstay treatment remains injectable insulin." (PMID 35890301, 2022). "Patients with this type of diabetes need to use insulin by external means to maintain blood sugar levels, usually by subcutaneous injection." (PMID 36099285, 2022). "Diabetes treatment typically relies on insulin or insulin analog injections for maintaining normoglycemia." (PMID 35563490, 2022). "The aim of the study is to determine the impact of a 12‐week intermittent fasting regimen compared with usual care in people with type 2 diabetes mellitus receiving insulin therapy." (PMID 35179802, 2022). "STZ selectively destroys pancreatic beta cells, leading to inadequate insulin secretion and diabetes." (PMID 35885283, 2022). "FA alone or in combination with insulin was administered in STZ-induced diabetic rats to treat diabetes-induced neuropathy." (PMID 36615475, 2022). "TRARG1 is a member of the glucose transporter family and plays an important role in glucose transport, diabetes and insulin response." (PMID 35647086, 2022). "Further, longitudinal data from the SEARCH for Diabetes in Youth and the Restoring Insulin Secretion studies have highlighted the morbidity in children with early type 2 (i.e., obesity-related) diabetes." (PMID 35498805, 2022). "In the past two decades, many drugs have been approved for the treatment of diabetes, e.g., insulin and its analogues, which increase the number of treatment options available for individuals with diabetes." (PMID 36613249, 2022). "Disruption of circadian rhythms is a risk factor for metabolic disorders and can lead to various metabolic diseases, including impaired insulin secretion, abnormal glucose tolerance, obesity, and even diabetes." (PMID 36531506, 2022). "When the duration of diabetes was >5 years, the choice of insulin among the clusters generally increased, as compared with the duration of ≤5 years, although the choice of non-insulin hypoglycemic agents was similar between the two durations." (PMID 36457559, 2022). "We also assessed diabetes when a person oral hypoglycemic agent and/or insulin and must have been diagnosed with T2DM in the 3rd or later decades of their life." (PMID 36741779, 2022). "Among the clinical parameters, basal insulin dose, diabetes duration, proteinuria, and HbA1c turned out to be the most reliable NH predictors." (PMID 36013211, 2022). "It has been reported experimentally that some Se compounds behave similarly to insulin, demonstrating a positive link between higher selenium levels and the prevalence of diabetes." (PMID 35478694, 2022). "It was shown in the Diabetes Control and Complications Trial that adolescents and adults on intensive insulin therapy gain significantly more weight, with an average increase of 4 kg more than those following conventional therapy." (PMID 35715954, 2022). "The effect of fatty pancreas on insulin secretion appears to be highly dependent on genetic predilection to diabetes and other metabolic profiles, and there are various inflammation severities of islets." (PMID 35327494, 2022). "Reactive oxygen species (ROS) formed in this process triggers tissue damage and has been shown to affect the two major mechanisms failing during diabetes: insulin resistance and insulin secretion." (PMID 36386935, 2022). "Nearly two-fifths of the sample were prescribed oral medication and insulin therapy for their diabetes." (PMID 35682513, 2022).
diabetes (continued). "This study assessed the association of hypoglycemic incidence and glycemic control between NPH and premixed insulin regimens in patients with type 2 diabetes mellitus (T2DM)." (PMID 36149907, 2022). "Lower minimal glucose and LC, and higher LBGI, DLV, CONGA-1, proteinuria, basal insulin dose, diabetes duration, and HbA1c, as well as the presence of autonomic neuropathy, formed the list of the 10 most reliable NH predictors assessed by RF with a 15 min PH." (PMID 36013211, 2022). "ACE played a role in vasoconstriction and fibrosis by binding to AT1, resulting in a significant reduction in insulin secretion, inducing and aggravating diabetes." (PMID 36699034, 2022). "Although PCPs report regularly filling insulin prescriptions for individuals with diabetes, they report low confidence in providing diabetes care, including diabetes technology management." (PMID 36589850, 2022). "In rodents, the administration of SCFA (in particular, butyrate) prevents diet-induced obesity and the development of diabetes by improving glucose control and insulin sensitivity." (PMID 35099411, 2022). "In this work, we investigated the potential antidiabetic therapeutic functions of phycocyanin in a high glucose high fat diet induced diabetes mellitus mouse model as well as an insulin-resistant SMMC-7721 hepatoma carcinoma cell model." (PMID 37430932, 2022). "Hyperglycemia, insulin resistance, and increased insulin levels in the case of diabetes lead to the development of diabetic cardiomyopathy." (PMID 36348778, 2022). "Reaching out to the diabetes nurse by telephone for advice on how to titrate insulin doses gave a sense of security." (PMID 35393314, 2022). "Fear of hypoglycemia is a fear specific to insulin-treated diabetes, which can lead to several unhelpful avoidance behaviors." (PMID 35830220, 2022). "Then, we have tested the action of the incretin pathway agonists on diabetes control and insulin requirement." (PMID 35227307, 2022). "The treatment by nanospheres (GA/LU/DIO-SeNPs) in the mice with diabetes for a period of 6 weeks restored their blood glucose, lipid profile, glycogen, glycosylated hemoglobin, and insulin levels." (PMID 36080407, 2022). "In the 100 years since the discovery of insulin, there have been significant technological advances in diabetes management." (PMID 35733769, 2022). "This interrupts insulin signaling, mediates insulin resistance and, eventually, results in diabetes mellitus." (PMID 35807304, 2022). "Of the established apelin isoforms, apelin-13 appears to be the most interesting in terms of diabetes therapy owing to its ability to improve glucose tolerance and insulin sensitivity, as well as potential effects to enhance insulin secretion." (PMID 35177945, 2022). "Thanks to residual insulin secretion, diabetes in WS is characterized by a lower insulin requirement, lower levels of HbA1c and a milder clinical course than type 1 diabetes mellitus." (PMID 35055657, 2022). "The prohibition of hypoglycemic events was important in the daily management of insulin-treated diabetes." (PMID 36572938, 2022). "Osteocalcin levels declined serially as glycemic status shifted from normoglycemia to prediabetes to diabetes, and showed significant associations with BMD, plasma glucose, insulin sensitivity and insulin secretion in the study population." (PMID 36686435, 2022). "Diabetes mellitus is characterized by hyperglycemia resulting from defects in insulin secretion, action, or both." (PMID 36297817, 2022). "Diabetes is a metabolic disorder characterized by lower responsiveness of tissues to insulin and consequent large variations in circulating levels of glucose." (PMID 36614008, 2022). "For example, upon detention at the Border refugees suffering with diabetes had to surrender medication such as insulin." (PMID 36454915, 2022).
diabetes (continued). "Given the unique immunoregulatory properties of SC that allow them to survive long-term as allografts and xenografts, we genetically engineered SC to deliver human insulin as a possible treatment for diabetes." (PMID 36555540, 2022). "Unfortunately, this is a complex task as diabetes is a progressive disease that requires the timely optimization of treatment, leading in majority of cases to insulin therapy." (PMID 36554673, 2022). "In diabetes, high glucose, insulin, and insulin resistance can affect the lipid metabolism: for example, the apoC-III encoding APOC3 gene expression is decreased by insulin and stimulated by glucose." (PMID 36419110, 2022). "CGA regulates the expression of enzymes and genes related to the glucose metabolic pathway, increases insulin sensitivity, and reduces glucose accumulation to inhibit the further development of diabetes." (PMID 35845802, 2022). "Some of the predictors of glycemic control in children in the literature include diabetes duration and insulin dose, age, care givers’ involvement in blood glucose monitoring, lipodystrophic changes at injection sites, and diet quality." (PMID 35705956, 2022). "In the early 1920s, the discovery of insulin revolutionized diabetes treatment and converted a rapidly fatal disease (especially for those with T1D) to a chronic condition." (PMID 35903090, 2022). "The study has a qualitative descriptive design, based upon nineteen in- depth interviews with persons diagnosed with insulin treated diabetes, analysed using qualitative content analysis." (PMID 35726172, 2022). "Studies have shown that resveratrol’s inhibition of insulin secretion is beneficial in patients with diabetes." (PMID 35739982, 2022). "Glucose-lowering agents other than SGLT2i had been prescribed in 79.5% of patients with diabetes; the most commonly used agent was metformin, followed by insulin and sulfonylureas." (PMID 35762322, 2022). "Heterozygous pathogenic variants in the INS gene result in MODY 10, which is a monogenic form of diabetes." (PMID 36361703, 2022). "The reduction in daily insulin needs and the optimization of glycemic control improves the patient’s quality of life, self-esteem, mental wellness, and diabetes-related morbidity and mortality." (PMID 36553284, 2022). "Pancreatic β-cell dysfunction and the ensuing impaired glucose-stimulated insulin secretion (GSIS) are essential for the progression from pre-diabetes to diabetes." (PMID 35326380, 2022). "Wistar rats with streptozotocin-induced diabetes had increased insulin sensitivity when exposed to water containing 10 ppm F, while Sprague Dawley rats exposed to water containing 15 ppm F had increased insulin resistance." (PMID 35208192, 2022). "Inhibition of PP2A or PTP1B is a viable approach toward improving insulin sensitivity for anti-diabetes therapy." (PMID 36014807, 2022). "miRNAs are critical regulators of glucose metabolism by regulating insulin metabolism in the pancreas and peripheral tissues, contributing to obesity and diabetes." (PMID 36010613, 2022). "Her insulin secretion presented with abnormal amounts and secretary modes, but most importantly, her diabetes completely reversed after discontinuation of capecitabine treatment." (PMID 35462530, 2022). "Diabetes mellitus is a disorder characterized by higher levels of blood glucose due to impaired insulin mechanisms." (PMID 35723349, 2022). "The study conducted a subgroup analysis, which revealed that diabetes patients with COPD had a more pronounced survival advantage for insulin adherence (insulin use rate ≥90%)." (PMID 36093107, 2022). "Diabetes is described as a chronic disease resulting from failure of the pancreas to generate enough insulin (type 1) or (type 1) inability of the body to efficiently utilize the insulin it generates." (PMID 35954993, 2022).